CD14 (CD14 molecule)
Diseases named in the same sentence as CD14 in open-access papers (continued):
Sharing a sentence is not in itself a finding about the gene and the disease.
ZIKV infection (19 papers, 2017 to 2026). "An in vivo and ex vivo study has demonstrated that CD14 monocytes from healthy pregnant women are susceptible to Zika virus infection." (PMID 36680261, 2023). "Michlmayr and colleagues analyzed PBMC susceptibility to ZIKV infection using a strain isolated in Nicaragua (Nica 2–16) and detected the infection mostly in CD14+CD16+ monocytes and in myeloid dendritic cells." (PMID 31752731, 2019). "Thus, the loss of detectable IL-2 after ZIKV infection in CD14-depleted PBMCs would further reduce NK cell priming." (PMID 29600283, 2018). "During the acute phase of ZIKV infection, the number of specific innate and adaptive cell types temporarily increased, including intermediate CD14+CD16+ monocytes, CD69 + NK, HLA‐DR+CD38+ non‐naïve CD8+ T cells, Th1 CD4+ T cells, and Tbet+ plasma cells." (PMID 41556482, 2026). "Zika virus infection induced differentiation of monocytes from the classical (CD14+ CD16−) to the intermediate (CD14+ CD16+) phenotype." (PMID 38247836, 2024). "CD14+CD16+ cells are the preferential targets of Zika virus infection, with amplified proliferation of these cells and a reduction in the percentage and number of classical CD14+CD16- monocytes." (PMID 32848776, 2020). "After whole blood infection with MR766 and H/PH/2013 isolates, ZIKV infection was observed in CD14+ monocytes." (PMID 31752731, 2019). "Levels of 11 mediators were significantly affected by the depletion of CD14+ monocytes, while 8 mediators were affected upon ZIKV infection." (PMID 29600283, 2018). "Previous investigation into ex vivo CD14+ monocytes and monocyte-derived macrophages showed significant differences in messenger RNA transcript abundance after ZIKV infection." (PMID 29672707, 2018). "Here, the transcriptomic consequences of ZIKV infection were studied systematically first in human peripheral blood CD14+ monocytes and monocyte-derived macrophages with high-density RNA sequencing." (PMID 29600283, 2018). "Data showed the involvement of various immune mediators during acute ZIKV infection accompanied by a general reduction in blood cell numbers for all immune subsets except CD14+ monocytes." (PMID 29672707, 2018). "ZIKV infection of PBMCs depleted of CD14+ monocytes significantly downregulated the expression of the various NK cell markers, demonstrating the functional role of monocytes as one of the key players for NK cell stimulation." (PMID 29600283, 2018). "Depletion of CD14+ monocytes in peripheral blood was then performed ex vivo to functionally understand the cross talk between monocytes and priming of NK cells during ZIKV infection." (PMID 29600283, 2018). "Among the most deregulated pathways affected by ZIKV infection in CD14+ monocytes included apoptosis, chemotaxis, cell proliferation, inflammation, acute phase response and mitochondria activation." (PMID 29167459, 2017). "CD14+ monocytes prime NK cell activity during ZIKV infection." (PMID 29600283, 2018). "Importantly, levels of monocyte chemoattractant protein 1 (MCP-1), IL-1RA, and vascular endothelial growth factor A (VEGF-A) were affected by both CD14+ monocyte depletion and ZIKV infection." (PMID 29600283, 2018). "Changes in the number of neutrophils (CD45+CD16+), monocytes (CD14+), B cells (CD19+), T cells (CD3+CD4+, CD3+CD8+), double-negative (CD3+CD4-CD8-) T (DNT) cells, NK cells (CD56+ and CD56hi) NK T cells (CD56+CD3+), and CD14+CD56+ cells during acute ZIKV infection were profiled." (PMID 29672707, 2018). "We stained for ZIKV intracellularly and confirmed that human CD14+ and CD20+ cells of the spleen and bone marrow are prone to productive ZIKV infection in these neonatal humanized mice." (PMID 36825016, 2023). "Intermediate (CD14+CD16+) monocytes have been shown to increase in the peripheral blood of children with acute infection and are themselves a major target for ZIKV infection." (PMID 35584677, 2022).
ZIKV infection (continued). "Further dissection of the monocyte populate into subpopulations showed that the percentage of classical monocytes (CD14+CD16-) also rapidly increased in the cirulating blood and peaked around 2–3 days post-ZIKV infection." (PMID 34120576, 2021). "Following ZIKV infection, higher percentage of monocytes (CD20-CD159a-CD14+cells) were detected in the blood after infection, with similar responses across the different ZIKV sub-lineages." (PMID 34120576, 2021). "Among infected donors, we observed ZIKV infection in CD3+CD4+ T cells, CD3+CD8+ T Cells, CD3−CD19+ B cells and CD14+ monocytes, albeit the relative numbers of infected subpopulations varied among donors." (PMID 31752731, 2019). "The effect of CD14+ monocyte depletion was observed in the levels of stem cell factor (SCF) and tumor necrosis factor alpha (TNF-α) only after ZIKV infection." (PMID 29600283, 2018). "Other than CD14+ monocytes, we sought to further identify the role of DCs during ADE of ZIKV infection triggered by DENV immune sera." (PMID 30044839, 2018). "We ruled out that a CD14-positive selection of monocytes influences the permissiveness of these cells for ZIKV infection due to stimulation of CD14 by using a non-CD14-based negative selection kit to isolate monocytes from PBMCs." (PMID 36560779, 2022). "Overall, we found alterations in the proportion of nonclassical monocytes during ZIKV infection, probably driven by the modification of their surface CD14 and CD16 expression." (PMID 34160241, 2021). "The percentage of non-classical monoctyes (CD14+CD16+) decreased following ZIKV infection with the lowest point reaching around 2–3 days post-infection." (PMID 34120576, 2021). "To more directly validate that primary human peripheral monocytes were the principal target cells supporting the enhancement of ZIKV infection in the presence of DENV immune serum, we positively enriched CD14+ monocytes from PBMCs via magnetic microbeads before performing virus inoculation." (PMID 30044839, 2018). "Notably, the increase in CD14+ CD16+ blood monocytes and plasma IL-8 observed here in the PTM model closely resemble the host response to ZIKV infection in humans." (PMID 30135445, 2018). "Some recent studies indicated CD14+ CD16+ monocytes to be the main target of ZIKV infection in PBMCs, and ZIKV infection induced a phenotypic shift within monocytes toward increased CD16 expression, suggesting a possible role of FcγRIII (CD16) during ADE of ZIKV infection." (PMID 30044839, 2018). "Interestingly, depletion of CD14+ monocytes and ZIKV infection did not affect the levels of epidermal growth factor (EGF), interleukin 9 (IL-9), IL-17A, macrophage inflammatory protein 1α (MIP-1α), and MIP-1β." (PMID 29600283, 2018). "Intriguingly, there appeared to be low but significant levels of ZIKV infection in CD14+ monocytes even in the absence of enhancing antibodies (naïve versus infected monocytes: 0.018±0.010 versus 0.040±0.025, P = 0.012), suggesting these may be the target cells of natural ZIKV infection." (PMID 30044839, 2018).
Arthritis (18 papers, 2009 to 2025). Inflammation of a joint. "Moreover, TLR4*AA/CD14*TT was significantly associated with arthritis occurrence in SLE patients (p = 0.01 after adjustment with age of onset and gender)." (PMID 24252506, 2013). "By assessing CD14+ DC3s circulating in the PB of patients with arthritis and those present in the SF, the local site of inflammation, we delineated how the microenvironment can affect DC3s." (PMID 40687784, 2025). "A similar profile of Notch receptors was already observed on CD14+ monocytes, with the altered expression in the synovial tissue affected by arthritis." (PMID 41213920, 2025). "To obtain insights into the functional capabilities of CD14−DC2s and CD14+ DC3s in the PB of patients with arthritis, we assessed the ability of sort-purified DC2s and DC3s to induce the proliferation of allogeneic T cells derived from HDs." (PMID 40687784, 2025). "To evaluate CD14+ DC3s in arthritis, we first compared their frequencies in the PB of patients with IA and healthy donors (HDs) using flow cytometry." (PMID 40687784, 2025). "Consistent with previous report in adult forms of arthritis, CD14+ infDCs were barely detectable in PB samples from both groups, but represent the major DC subset in SF." (PMID 32849606, 2020). "Recent publications have shown that the CD14+CD16- inflammatory subset of monocytes is associated with increased and chronic inflammation and the development of arthritis." (PMID 31449558, 2019). "The CD14 (-159)*T allele seems to be associated with susceptibility to SLE and arthritis occurrence." (PMID 24252506, 2013). "Analysis of these SNPs according to clinical and biological features showed a significant higher frequency of arthritis in SLE patients carrying CD14*T/T genotype (92%) comparatively to those with C/C and C/T genotypes (72.5%), p = 0.04." (PMID 24252506, 2013). "All data considered, differences in detected CD1c+CD14+ DC3s frequencies might be related to the type of arthritis, onset of disease, and disease activity." (PMID 40687784, 2025). "The resistance to spontaneous and Fas-mediated death of SF-derived CD14+ cells may be a general feature of cells from the site of active inflammation in arthritis, since similar observations were made in PsA." (PMID 28118944, 2017). "Moreover, SLE patients carrying CD14*T/T/TLR4*A/A haplotype had significantly more arthritis (91.3%) than the rest of SLE group (73%), p = 0,044 and confirmed by multivariable analysis after adjustment according to age and gender, p = 0.01." (PMID 24252506, 2013). "Examination of CD14 SNP according to clinical and biological features of SLE showed a significant association of the homozygous mutated genotype CD14*T/T with the occurrence of arthritis; p = 0.04, OR (95% CI) = 4.35 [0.9-28.6]." (PMID 24252506, 2013). "In this study we analysed the peripheral blood components, i.e. CD14+ monocytes, CD4+, CD8+ and CD56+T lymphocytes (CD3+), CD80+, C-X-C chemokine receptor 3 (CXCR3)+, CD27+ B lymphocytes (CD19+) and CD16+CD56+CD3− NK cells, for their association with arthritis development." (PMID 27629388, 2016). "The presence of CD1c+CD14+CD163+ DC3s in SF from patients with arthritis aligns with the reports of CD163+ DC3s detected in SF and tissue in OA, and CD1c+CD14+ DCs described in inflammatory tumor ascites and RA SF." (PMID 40687784, 2025). "MPC treatment 1 day after arthritis induction appeared to greatly limit the recruitment of CD4+ T cells and CD14+ monocytes and macrophages (by around 40%) to the synovium." (PMID 28173831, 2017). "It was demonstrated that non-classical CD14+CD16++ monocytes can differentiate into inflammatory macrophages and play a key role in joint inflammation in a mouse model of arthritis." (PMID 34206012, 2021).
chronic kidney disease (18 papers, 2013 to 2025). Impairment of the renal function secondary to chronic kidney damage persisting for three or more months. "In individuals with chronic kidney disease, increased numbers of CD14++CD16+ intermediate monocytes were associated with higher cardiovascular mortality suggesting a detrimental role for these cells." (PMID 35549955, 2022). "Intermediate CD14++CD16+ monocytes were shown to predict cardiovascular events in patients with chronic kidney disease and a broad patient population at cardiovascular risk." (PMID 34206012, 2021). "Elevated circulating CD14 is observed in patients with chronic kidney disease, and is reportedly associated with mortality among patients on dialysis." (PMID 28522940, 2017). "Patients with chronic kidney disease (CKD) exhibit elevated CD14++CD16+ pro-inflammatory monocytes in bone marrow alongside heightened systemic levels of IL-6, IL-1β, and TNF-α, suggesting persistent innate immune activation." (PMID 40746537, 2025). "(A–C) CD14+ monocytes from end-stage renal disease (ESRD) patents (n=10) and age-matched healthy controls (HCs) (n=11) were rested for 6 days and stimulated by lipopolysaccharide (LPS) (10 ng/ml) for 24 hrs (A)." (PMID 38980302, 2024). "In patients with chronic kidney disease, the CD14++CD16+ subset independently predicted cardiovascular outcome, while the classical subset was proven to be predictive for cardiovascular events in a general population." (PMID 25849089, 2015). "CD14++CD16+ monocytes have independently been associated with cardiovascular events in nondialysis patients with chronic kidney disease and in subjects referred for elective coronary angiography." (PMID 28446249, 2017). "In addition, higher numbers of pro-inflammatory CD14+CD16+ monocytes were detected in patients with end-stage renal disease compared to healthy controls." (PMID 23922945, 2013). "Intermediate (CD14++CD16+) monocytes have important pro-inflammatory and atherogenic features and are increased in patients with chronic kidney disease (CKD)." (PMID 31308443, 2019). "We previously found that patients with abdominal aortic aneurysms (AAAs) have higher CD14+CD16+ monocyte frequency and prevalence of moderate chronic kidney disease (CKD) than age-matched control subjects." (PMID 26925780, 2016).
non-small cell lung carcinoma (18 papers, 2013 to 2025). A group of at least three distinct histological types of lung cancer, including non-small cell squamous cell carcinoma, adenocarcinoma, and large cell carcinoma. "Patients with non-small cell lung cancer have B7-H3 predominantly expressed on intratumoral CD14+HLA-DR/low MDSC and is associated with NSCLC progression." (PMID 36620544, 2022). "Here, we report elevated frequencies of CD14+ cDC2s, which restore to normal frequencies after tumor resection, in non-small cell lung cancer patients." (PMID 38242119, 2024). "For instance, a functional analysis in non-small cell lung carcinoma revealed that follicular helper T cells were capable of promoting the differentiation of regulatory B cells and CD14+ human leukocyte antigen (HLA) - DR - cells." (PMID 37538124, 2023). "A prvious study found that the IL-33/ST2 axis enhances lung-resident CD14+ monocyte function in patients with non-small cell lung cancer." (PMID 37719702, 2023). "M-MDSCs (CD33+CD14+IL-4Rα+ cells) are elevated in non-small-cell lung cancer (NSCLC) patients and are S100A9+." (PMID 36831371, 2023). "Apart from NK cells, supernatant from PD-1high ILC2s infiltrating non-small cell lung cancer (NSCLC) enhanced polarization of healthy CD14+ myeloid cells into M2-like macrophages through IL-4 and IL-13." (PMID 35565201, 2022). "More recently, it has been reported that the suppressive activity of human MDSCs resides in a CD14+S100A9+ inflammatory monocytes in non-small cell lung cancer (NSCLC) patients 25]." (PMID 23437326, 2013). "In a study in patients with advanced non-small cell lung cancer granulocytic (CD11b+ CD14- CD15+) MDSCs were increased in blood." (PMID 23320561, 2013). "Immune profiling studies on non-small cell lung cancer (NSCLC), renal cancer and melanoma PDOs demonstrated retention of CD8+ and CD4 + T cells, CD14/CD69+ macrophages, NK and NKT cells and B cells." (PMID 37438470, 2023). "We co-cultured T cells with sorted CD14+ HLA-DR low/neg CD33high M-MDSC from either T1D patients, patients with non-small cell lung cancer or HD in an indicated ratio (MDSC/ T cell 1:1, 1:2 and 1:4 ratio)." (PMID 33206686, 2020). "For instance, immune profiling studies on non-small cell lung cancer (NSCLC), renal cancer, and melanoma PDOs with TIME have revealed that the CD8+ and CD4+ T cells, CD14/CD68/CD 69+ macrophages, NK (natural killer), NKT (natural killer T) and B cells were well-maintained in tumor PDO models." (PMID 38256166, 2024). "Using a non-small cell lung cancer dataset (n = 153) as a case study, we found that the spatial heterogeneity in the TME cellular composition of CD14+ cells, CD19+ B cells, CD4+ and CD8+ T cells, and CK+ tumor cells, had a significant non-zero effect on the overall survival (p = 0.027)." (PMID 37756338, 2023). "Interestingly, a novel subset of Lin− HLA-DR− CD33+ CD11b+ CD14+ CD15+ has been reported in a study of non-small cell lung cancer (NSCLC), in which the CD14+ CD15+ population was revealed to have a satisfactory prognostic value in untreated patients." (PMID 34689842, 2021). "Furthermore, increased myelomonocytic markers like CD14 and CD163 were detected after macrophage differentiation by soluble mediators of non-small cell lung carcinoma cell lines." (PMID 25902944, 2015).